AGT (angiotensinogen)
Diseases named in the same sentence as AGT in open-access papers (continued):
Sharing a sentence is not in itself a finding about the gene and the disease.
preeclampsia (continued). "Although, the peripheral RAS (plasma levels of active renin, renin and Ang II) is downregulated in the DOCA preeclampsia model; the association of gene polymorphisms of RAS and preeclampsia was observed in human, moreover, T allele of angiotensinogen may involve in the pathogenesis of PE." (PMID 29085302, 2017). "Urinary AGT represents a biomarker for the upregulation of RAAS and is subsequently increased during PE and gestational hypertension (GH)." (PMID 38411777, 2024). "In late-onset preeclampsia, the placental expression of miR-378, which is predicted to target REN and ACE mRNAs, miR-514b-3p, predicted to target AGT and AGTR1 mRNAs and miR-892c-3p, which targets AGT mRNA, were increased." (PMID 31551925, 2019). "We have shown, for the first time, that urinary AGT—a marker of activated intrarenal RAS—is significantly increased in women with both GH and preeclampsia." (PMID 31237175, 2019). "Women with preeclampsia have been seen to have lower circulating levels of RAS factors, however, AngII levels, angiotensinogen and Agtr1 receptor mRNA is increased in placentae of preeclamptic women." (PMID 26260700, 2015). "Preclinical studies in rats using angiotensinogen siRNA in preeclampsia models did not demonstrate adverse effects on offspring, nor was placental transfer detected; however, these findings are insufficient to establish safety in humans." (PMID 41226756, 2025). "Although the extent of the RAS component expression has been investigated in placentas affected by FGR, either idiopathic or due to preeclampsia, there has, to our knowledge, been no investigation of angiotensinogen in the amniotic fluid." (PMID 38398716, 2024). "In contrast, Figure 5B2 and 5C2 show the absence of AGT protein in glomeruli from the GH and preeclampsia patients, although Figure 5B1 and 5C1 demonstrate AGT in the proximal tubules." (PMID 31237175, 2019).
kidney damage (108 papers, 2008 to 2025). "The activation of the intrarenal RAS is associated with increased urinary angiotensinogen (uAGT), blood pressure (BP), and kidney damage." (PMID 38203807, 2024). "The C risk allele in the present study among Filipinos corresponds to the missense mutation (M[ATG] > T[ACG] at amino acid position 235) in the AGT gene, the consensus risk variant for nephropathy." (PMID 39561140, 2024). "Concurrently, the RAS amplifies oxidative stress and inflammation; IR-induced kidney damage increases renin, converting angiotensinogen to angiotensin I and then II (Ang II) via ACE." (PMID 40563698, 2025). "SNPs within the angiotensinogen (AGT) and angiotensin II receptor, type 1 (AT1) genes are also associated with a higher risk of developing nephropathy." (PMID 24705265, 2013). "Recently, the non-clipped kidney was found to have increased mRNA, protein and urinary levels of angiotensinogen, suggesting that kidney damage occurs through increased AngII, and that angiotensinogen could be used as an early biomarker of kidney damage." (PMID 27935823, 2016). "For example, the homozygous AGT (angiotensinogen gene) 235-T/T genotype has been associated with faster progression to ESRD in patients with glomerulonephritis and with susceptibility to nephropathy in patients with type I diabetes mellitus, although not in two populations with type 2 diabetes." (PMID 19327134, 2009). "Accordingly, higher urinary excretion levels of AGT and renin might be unique ADPKD features that are not simply a consequence of elevated plasma RAAS concentrations and renal function decline, but might be contributors to kidney damage." (PMID 38027263, 2023).
lung fibrosis (94 papers, 2004 to 2025). "A previous report showed that the G-6A polymorphism of the AGT gene is associated with increased angiotensin production and idiopathic pulmonary fibrosis progression, which is associated with increased risk of lung cancer." (PMID 33353148, 2020). "Genetic data linking AGT polymorphisms to the severity of disease in Idiopathic Pulmonary Fibrosis are also discussed." (PMID 22500179, 2012). "Pulmonary fibrosis induced by bleomycin is associated with increased AGT and AngII concentrations in lungs of a rat model." (PMID 30530571, 2019). "In the bleomycin-induced pulmonary fibrosis model, AGT expression is rapidly upregulated in blood-free lung tissue." (PMID 22500179, 2012). "First, however, the evidence that lung-derived angiotensinogen is involved in pulmonary fibrosis will be described." (PMID 22500179, 2012). "The overexpression of AGT could lead to the apoptosis of alveolar epithelial cells and pulmonary fibrosis." (PMID 33511766, 2021). "All major components of the RAS exhibit profibrotic activity, such as Angiotensin converting enzyme (ACE) and angiotensinogen may contribute to increased Ang II production, and Ang II plays important roles in the development of renal, hepatic, as well as pulmonary fibrosis." (PMID 35685407, 2022). "Angiotensinogen (AGT) is an precursor in tissue renin-angiotensin system (RAS) that plays an important role in promoting the development of hepatic fibrogenesis, renal interstitial fibrosis, and idiopathic pulmonary fibrosis." (PMID 34424905, 2021). "Concerning the correlation of lung fibrosis with RAS, hyperoxia increases the collagen and α-smooth muscle actin (α-SMA) expression via RAS components including angiotensinogen and ACE, and angiotensin II expression is also significantly increased by hyperoxic exposure in human lung fibroblasts." (PMID 23762250, 2013). "Furthermore, in biopsy specimens obtained from the lungs of patients with Idiopathic Pulmonary Fibrosis (IPF), AGT mRNA and protein were 21-fold and 3.6-fold more abundant, respectively, in IPF biopsies relative to biopsies of normal human lung." (PMID 22500179, 2012).
atrial fibrillation (92 papers, 2008 to 2026). A disorder characterized by an electrocardiographic finding of a supraventricular arrhythmia characterized by the replacement of consistent P waves by rapid oscillations or fibrillatory waves that vary in size, shape and timing and are accompanied by an irregular ventricular response. "Therefore, we investigated the association of tSNPs in RAS gene (ACE gene rs8066114, AGT gene rs7539020, rs3789678, rs2478544, rs11568023, rs2478523, rs4762, rs699 and CYP11B2 rs3802230, rs3097) and atrial fibrillation in a Chinese Han sample." (PMID 25723521, 2015).
Stroke (91 papers, 2006 to 2026). Sudden impairment of blood flow to a part of the brain due to occlusion or rupture of an artery to the brain. "Agt is the gene encoding angiotensinogen, and current studies have shown that its polymorphism is closely related to stroke, especially cerebral small vessel disease." (PMID 35027937, 2022). "Studies analyzing the association between angiotensinogen (AGT) promoter polymorphism and stroke have indicated that polymorphic alterations of the AGT promoter modulate its transcriptional activity and cause cerebral vascular diseases." (PMID 22242192, 2012). "The aim of this study was to assess whether AGT SNPs were associated with the development and clinical features of stroke, specifically ischemic stroke (IS) and intracerebral hemorrhage (ICH) in a Korean population." (PMID 23251296, 2013). "Regarding stroke cases, polymorphisms in some genes such as MTHFR, eNOS, ACE, AGT, ApoE, PON1, PDE4D were associated with a higher risk of ischemic stroke." (PMID 38478535, 2024). "Bmal1–/– mice play an important role in the circadian rhythm of blood pressure changes in stroke by impairing the transcriptional level of angiotensinogen (Agt), thereby exhibiting a super-dipper phenotype in the nocturnal phase." (PMID 36570843, 2022). "Angiotensinogen AGT 174T/235M/-6A, AGT 174T/235T/-6G.AGT 174T/235T/- 6A and AGT 174M/235T/-6A haplotypes weresignificantly associated with an increased risk of stroke." (PMID 25962947, 2015). "It is not clarified whether these mice models show ischemic stroke; however, these hypertensive mice, especially renin and angiotensinogen transgenic mice, are useful for experimental stroke research." (PMID 23431245, 2013). "Subsequently, a spontaneous stroke model using human renin and angiotensinogen transgenic hypertensive mice, but not Tsukuba hypertensive mice, was reported." (PMID 23431245, 2013).
liver fibrosis (82 papers, 2010 to 2025). "For example, the inheritance of variants in TGF-β1 and AGT together is associated with increased staging of hepatic fibrosis." (PMID 22500179, 2012). "Renin activates the conversion of angiotensinogen in Ang I (angiotensin I), which is turn to Ang II (angiotensin II) and has an overwhelming importance like the growth hormone in liver fibrosis." (PMID 25870693, 2014). "Another study also reported that polymorphisms induce high angiotensinogen and TGF-β1, the most abundant isoform of TGF-β, are associated with advanced hepatic fibrosis in patients with NAFLD." (PMID 23840852, 2013). "This was also reflected in the disease progression of liver injury following chronic hepatitis C infection, in which liver fibrosis severity was highly associated with genotypes leading to higher expression of TGF-β1 and AGT." (PMID 22500179, 2012). "Interesting, it was observed that a direct inhibition of AGT in pro-fibrotic cells could attenuate the progression of hepatic fibrosis in the early stage." (PMID 34424905, 2021). "For example, the combination of angiotensinogen (ATG) gene variant c.1-44 and transforming growth factor beta (TGFβ1) p.R25P is associated with advanced hepatic fibrosis in obese patients with non alcoholic fatty liver disease but not in patients with other chronic liver diseases." (PMID 20170533, 2010).
Sepsis (82 papers, 2008 to 2026). Sepsis is defined as life-threatening organ dysfunction caused by a dysregulated host response to infection. "AGT siRNA therapies show promise for restoring BP in emergencies, such as hypovolemia, hypotension due to hemorrhage or sepsis, and acute renal injury." (PMID 39852196, 2024). "Removing the AGT gene from the liver of mice reduced levels of angiotensin II and alleviated sepsis-induced myocardial dysfunction." (PMID 37510681, 2023). "More studies are needed to establish the benefits of inhibiting AGT in sepsis and other infectious disease models." (PMID 35904033, 2022). "Noteworthy, u-AGT was also reported to be a potential prognostic tool to identify patients in risk of worse outcomes related to AKI of multiple etiologies, including sepsis-associated AKI." (PMID 36359365, 2022). "Hepatocyte-specific deletion of AGT mitigates sepsis-induced myocardial dysfunction through both Ang II-dependent and independent mechanisms in mice." (PMID 35904033, 2022). "A recent post hoc analysis of the Vitamin C, Thiamine, and Steroids in Sepsis (VICTAS) Trial utilized different methods for RAAS quantification, including ELISA for angiotensinogen measurement, radioimmunoassay for peptide levels, and fluorescence assays for enzyme activities." (PMID 40126750, 2025).
glomerulosclerosis (80 papers, 2006 to 2025). A hardening of the kidney glomerulus caused by scarring of the blood vessels. "Nevertheless, AGT siRNA offered renoprotection in this model (a reduction in glomerulosclerosis and diminished proteinuria), and this involved the suppression of renal Ang II independently of any blood pressure–lowering effect." (PMID 37855126, 2023). "Intramedullary infusion of sodium butyrate in uninephrectomized rats resulted in the reversal of angiotensin-II-induced glomerulosclerosis and decreased the expression of the (pro)renin receptor, angiotensinogen, renin, angiotensin-I-converting enzyme and renal inflammatory markers." (PMID 36678139, 2023). "MR antagonism increases CuZn-SOD and Mn-SOD, alleviates glomerulosclerosis and proteinuria, and decreases renal (pro)renin receptor protein expression, angiotensinogen levels, AT1 receptor mRNA levels, and kidney Ang II content." (PMID 39765782, 2024). "Yet, only AGT siRNA with or without valsartan restored podocyte foot processes and reduced glomerulosclerosis." (PMID 37855126, 2023). "The PAS staining results identified glomerulosclerosis accompanied by intrarenal RAS activation, which manifested as increased levels of Ang II in the plasma and kidney, and increased levels of renal renin, AT1R and AGT expression, which was consistent with the results of previous study." (PMID 24944606, 2014).
metabolic syndrome (79 papers, 2007 to 2026). A cluster of metabolic risk factors for CARDIOVASCULAR DISEASES and TYPE 2 DIABETES MELLITUS. "This study was performed to demonstrate urinary angiotensinogen as a potential prognostic marker of the albuminuria reduction effects of olmesartan in patients with metabolic syndrome." (PMID 27801805, 2016). "Therefore, this study aims to investigate the association between the AGT M235T gene polymorphism and hypertensive IHD complications and to evaluate the role of dyslipidemia in the development of IHD in the Ethiopian population." (PMID 40717713, 2025). "Based on the findings in this study, treatment with ARB might be recommended in untreated patients with metabolic syndrome who showed a higher value of urinary AGT before treatment." (PMID 27801805, 2016). "Our data demonstrate that olmesartan, an ARB, could decrease urinary excretions of albumin, as well as AGT in patients with metabolic syndrome." (PMID 27801805, 2016). "In addition, we show that urinary AGT excretion could be a prognostic marker of the albuminuria reduction effects of ARB in patients with metabolic syndrome." (PMID 27801805, 2016). "This study was performed to demonstrate that an ARB could exert albuminuria reduction effects in patients with metabolic syndrome and that urinary AGT excretion could be a prognostic marker of the albuminuria reduction effects of ARB in patients with metabolic syndrome." (PMID 27801805, 2016). "Therefore, urinary angiotensinogen could be a prognostic marker of the albuminuria reduction effects of olmesartan in patients with metabolic syndrome." (PMID 27801805, 2016). "Kamide, in a cell culture study, reported that insulin increased the expression of angiotensinogen and angiotensin II, thus it may be possible that cardiovascular events in subjects with metabolic syndrome could be reduced with the use of agents that block RAAS." (PMID 25582547, 2015). "The present data demonstrated that an ARB, olmesartan, could decrease urinary excretions of albumin, as well as AGT, suggesting that an ARB has albuminuria reduction effects in patients with metabolic syndrome." (PMID 27801805, 2016). "While dyslipidemia was a significant risk factor for IHD in our study, no direct association was found between the AGT gene polymorphism and dyslipidemia, suggesting that other genetic or environmental factors may play a role." (PMID 40717713, 2025). "However, the effect of ARB on urinary AGT has not yet been examined in patients with metabolic syndrome." (PMID 27801805, 2016).
congestive heart failure (76 papers, 2006 to 2025). Failure of the heart to pump a sufficient amount of blood to meet the needs of the body tissues, resulting in tissue congestion and edema. "A previous report indicated that gene expression of (P)RR, renin, and angiotensinogen is increased in the heart with chronic heart failure in rats." (PMID 34367278, 2021). "In congestive heart failure (CHF) in rats, changes in angiotensinogen and AT1R expression have been described in the periventricular nucleus (PVN)." (PMID 33946230, 2021).
type 2 diabetes (76 papers, 2004 to 2025). "RREB1, initially identified as a repressor of the angiotensinogen gene, is associated with type 2 diabetes in African Americans with end stage kidney disease." (PMID 38812969, 2024). "Urine AGT is associated with GFR loss over 2 years of follow‐up in type 2 diabetes, even after adjustment for baseline proteinuria and GFR." (PMID 24793984, 2014). "In contrast to the majority of previous publications of AGT1R and AGT polymorphisms, this study only included adults with type 2 diabetes, which is a population especially at high risk for kidney dysfunction and CHD." (PMID 19327134, 2009). "A total of eleven of genes were differently expressed in celiac patients compared with disease controls of which CD36, CD38, FOXP1, SELL, PPARA, PPARG, AGT previously associated with type 2 diabetes and AKAP6, NTNG1 with anorexia nervosa remained significant after correction for multiple testing." (PMID 27483138, 2016). "Polymorphisms in AGT have been associated with metabolic syndrome, type 2 diabetes mellitus (T2D), hypertension, and altered insulin sensitivity." (PMID 41300761, 2025). "Treatment with SGLT2 inhibitors significantly lowered urinary AGT levels and renal AGT expression in animal models of type 2 diabetes, and a similar tendency was observed in patients with type 2 diabetes." (PMID 35710133, 2022). "Urinary excretion of AGT has been proposed as a biomarker of intrarenal RAS activation in patients with type 2 diabetes." (PMID 33933156, 2021). "Our data showed that changes in urinary intact angiotensinogen excretion were similar to those in urinary total angiotensinogen in patients with type 2 diabetes." (PMID 28596160, 2017). "We conducted a descriptive case study to examine the effects of sodium-glucose cotransporter 2 (SGLT2) inhibitors on urinary angiotensinogen excretion, which represents the function of the intrarenal renin–angiotensin system, in patients with type 2 diabetes." (PMID 28596160, 2017). "Polymorphisms in AGT1R and AGT genes are associated with renal dysfunction and CHD in type 2 diabetes and further support the important role of the RAS in these complications." (PMID 19327134, 2009). "Importantly, several studies have indicated a higher urinary AGT/creatinine ratio in patients with type 2 diabetes than in patients with type 1 diabetes." (PMID 30717173, 2019). "Furthermore, in renal tissues of type 2 diabetic rats and patients, gene expression of angiotensinogen was significantly increased in the kidney." (PMID 29600408, 2018). "Therefore, we conducted a descriptive case study to examine the effects of SGLT2 inhibitors on urinary angiotensinogen in patients with type 2 diabetes." (PMID 28596160, 2017). "We found that the baseline urinary total angiotensinogen/creatinine ratio in patients with type 2 diabetes was approximately 50 μg/g, which is much higher than in patients with type 1 diabetes, 25 suggesting that intrarenal RAS is activated by augmentation of angiotensinogen." (PMID 28596160, 2017). "Finally, we investigated the correlation between AGT expression levels and renal dysfunction in patients with type 2 diabetes." (PMID 24284398, 2013). "In patients with type 1 or type 2 diabetes, we found that urinary AGT levels were significantly higher in pre-albuminuric patients with type 1 diabetes than in control subjects and that ARBs reduced urinary AGT excretion in patients with type 2 diabetes." (PMID 24284398, 2013). "Sex may modify associations between AGT1R 1166 C-allele and AGT 235T and CHD in type 2 diabetes." (PMID 19327134, 2009). "Increased activation of the renin-angiotensin system (RAS) may be important in promoting coronary heart disease (CHD) and renal dysfunction, but limited data are available on associations between angiotensin type 1 receptor (AGT1R) and angiotensinogen (AGT) genotypes in type 2 diabetes." (PMID 19327134, 2009).